CCND2 (cyclin D2)
Diseases named in the same sentence as CCND2 in open-access papers (continued):
Sharing a sentence is not in itself a finding about the gene and the disease.
cancer (continued). "While CCND2, a cell cycle regulator, VEGFA, an essential regulator of angiogenesis in a variety of cancer types and BRAF, an oncogene in a variety of cancers, most likely serve as our “proof of concept” genes for demonstrating functional significance in human ERMS." (PMID 24009521, 2013). "Upregulation of cyclin D2 and CDK6 has been observed in cancers." (PMID 23024765, 2012). "BCL6 was highly expressed in cyclin D2-negative cases and was remarkably reduced in cyclin D2-positive cancer cases in the HB-EGF-positive group." (PMID 19337254, 2009). "In addition to these key driver genes, our analysis has also identified CCND2 and CHD1, which are known to be involved in various types of cancer but have not previously been linked to DN or T2D." (PMID 38966710, 2024). "Both in vitro and in vivo studies have consistently confirmed the anti-cancer potential of fucoidan via the inhibition of angiogenesis, induction of cell cycle arrest and apoptosis and down regulation of CDK4, cyclin D1 and cyclin D2 in cancer cells [reviewed in more details in and]." (PMID 36874031, 2023). "Moreover, it was reported a lack of expression of cyclin D2 in primary breast carcinomas, in contrast to normal breast tissue and other cancers." (PMID 37568789, 2023). "In PCa, hypermethylation of RARβ, cyclin D2 (CCND2), GSTP1, MGMT and hypomethylation of MYC, uPA, PLAU, S100P, may promote cancer cell proliferation, progression and metastasis and lead to poor clinical outcomes." (PMID 35517510, 2022). "Sequencing results showed that Wnt7a, Wnt7b, Fzd2, Mmp7 and Ccnd2 in the Wnt signaling pathway were downregulated after PRDX6 knockout, suggesting that this signaling pathway may be involved in the regulation of PRDX6's cancer-promoting effect." (PMID 36209344, 2022). "Interestingly, we observed that DLL1 downregulation considerably increased the mRNA levels of Cyclin D2, a G1/S transition gene, whose expression is very low or absent in some human cancers due to promoter hypermethylation." (PMID 31107884, 2019). "There is a great deal of overlap between CCND2, G1/S-specific cyclin D2, and STAT3, including the prolactin and FOXO signaling pathways, which are inactivated by major oncogenic signals such as the PI3K and MAPK pathways, and their expression is also repressed by microRNAs in multiple cancer types." (PMID 29992138, 2018). "Post-treatment samples may also acquire mutations in known cancer driver genes (for example, SF3B1, TAF1 and CCND2) that are absent from the paired pre-treatment sample." (PMID 27045317, 2016). "In addition, cancer cell line spheroids sustained activation of Akt, expression of cyclin D2 and did not display any activation of caspase-3." (PMID 17567918, 2007). "Notably, we showed that three cancer samples did not express cyclin D2 in the absence of methylation." (PMID 12771922, 2003). "Moreover, H6-PTEN cells exhibited cancer stem cell (CSC)-like properties, along with high expression of aldehyde dehydrogenase 1 and CD44s, a large ALDH 1high population, enriched spheroid formation, and β-catenin-mediated upregulation of cyclin D2, which is required for persistent CSC growth." (PMID 36411429, 2022). "By comparing the lists of top-ranking cancer-related target genes, we were able to identify seven promising cancer-related genes that may be targets of the hsa_circRNA_100395/miR-141-3p/ miR-200a-3p axis in PTC (in order of descending rank): E2F3, GLS, CCND2, PTEN, CCNG1, CDC25B, and ZFPM2." (PMID 28288173, 2017). "In cell-based and in vivo cancer models, only DNMT3B enzymatic activity, and not DNMT1 or DNMT3A, affects Ccnd2 expression." (PMID 36739439, 2023). "Four post-treatment cancers also showed focal copy number gains of ERBB2, CCND2, TERT and CCNE1 that were absent from the pre-treatment samples." (PMID 27045317, 2016).
cancer (continued). "From limited sample material, we detected integration events in 2,749 cells and found no integration events at genomic loci associated with clonal expansion after gene therapy near LMO2, IKZF1, CCND2, HMGA2, or MECOM, and no overrepresentation near cancer-related genes." (PMID 39532107, 2025).
infection (11 papers, 2010 to 2025). The state of being infected such as from the introduction of a foreign agent such as serum, vaccine, antigenic substance or organism. "CCND2 encoding cyclin D2 is the first EBNALP-induced gene identified, is maximally expressed on day 3 post infection and is essential for LCL establishment and growth (Fig. EV2C)." (PMID 39747661, 2025). "Proviral DNA formation was also enhanced in cyclin D2 and p21 knockdown GM-CSF macrophages in short-term infections with the fully replicative HIV-1 R5-tropic strain BaL (roughly 3-fold increase, p = 0.007 for siCCND2 and p = 0.03 for siCDKN1A respectively)." (PMID 27541004, 2016). "These experiments revealed that EBV infection induced p16INK4a transcription in the first few days after infection – when EBNA2 transactivates directly (eg c-MYC) or indirectly (eg cyclin D2) inducers of cell cycle progression and hyperproliferation." (PMID 23436997, 2013). "We also found the cyclin D2 transcript down regulated only during time of infection in MDCK cell lines which mimics a mammalian model of study." (PMID 21529348, 2011). "Importantly, confirmatory siRNA sequences targeting Cyclin D2 showed similar effects on infection and proviral DNA formation after HIV-1 BaL infection, indicating that cyclin D2 acts as part of a viral restriction mechanism in GM-CSF macrophages." (PMID 27541004, 2016). "Our data are unclear as to whether (as previously reported) EBNA-LP enhances the activation of CCND2 (indirectly regulated by EBNA2), as the modest reduction in its transcription early after infection of EBNA-LP deficient cells could also be due to their reduced proliferation." (PMID 29462212, 2018). "We identified ten NK subgroup-specific marker molecules (Kcnj8, Cmah, Ccnd2, Cx3cr1, Thy1, Tnfrsf9, Zbtb20, Gng11, CD226, Egr3) from C0 to C9 and assessed their expression changes during infection using RT-qPCR." (PMID 40244063, 2025). "In cultured VSMCs, treatment with PGE1-OH or infection of Ad-EP4 also significantly upregulated the mRNA levels of genes related to cell proliferation including Ki67, Foxm1, Ccna2, Ccnb1, Ccnd1, Ccnd2, Ccne1, and CDK2." (PMID 36078128, 2022). "In addition, we determined expressions of CCND1, CCND2, CCNE1 and pRb in rat hypertrophic myocardium after 2-week infection with recombinant miR-16 adenovirus." (PMID 25583328, 2015). "These experiments revealed that infection with a “wild type” EBV modestly induced p16INK4a transcription in the first few days after infection – when EBNA2 transactivates inducers of cell cycle progression (e.g., MYC and cyclin D2) and a period of hyperproliferation has been described." (PMID 24167519, 2013). "The overwhelming majority of changed miRNAs were downregulated after infection and infection plus SP-A2 (1A0) protein rescue, and these were predicted to target genes that play a role in cell cycle and growth and proliferation pathways, such as CCND1, CCND2, CDK7, CDKN2A, E2F1, E2F2, E2F3, and MYC." (PMID 35844510, 2022).
hematologic malignancies (4 papers, 2017 to 2025). "CCND2 encodes a G1 cyclin that is subject to activating mutations, translocations, and transcriptional upregulation in hematologic malignancies, supporting its role as a potential effector of IKAROS-mediated enhancer repression." (PMID 41509392, 2025).
adenocarcinoma (2 papers, 2019 to 2021). A common cancer characterized by the presence of malignant glandular cells. "Data from the Cancer Genome Atlas (TCGA) database indicated statistically significant negative correlation between PICOT and CCND2 in eight different human tumors where the highest correlation was in lung (p = 8.67E−10) and pancreatic (p = 1.06E−5) adenocarcinoma." (PMID 31527584, 2019). "We found that MAPK inhibition failed to reduce the MCM2 rate in control adenocarcinomas, whereas the MCM2 rate declined in tumors with Cyclin D2 knockdown upon RAF/MEK inhibitor treatment." (PMID 33821796, 2021).
colon polyps (1 paper, 2005). "Moreover, in colon polyps, the overexpression of cyclin D2 was reported to be the most considerable aberration among several G1-phase regulators, indicating that the overproduction of cyclin D2 protein is an early event in neoplastic transformation of the colon." (PMID 16012517, 2005).
digestive tumours (1 paper, 2024). "Our analysis of PPI networks identified 11 hub genes (Myd88, Traf6, Irf7, Cdk4, Ccnd2, Mapkap1, Prr5, Mpp3, Serpinb6b and Pvrl3) that were implicated in digestive tumours." (PMID 38434966, 2024). "The PPI networks identified 10 hub genes that were implicated in digestive tumour immunotherapy target TIM-3 (Myd88, Traf6, Irf7, Cdk4, Ccnd2, Mapkap1, Prr5, Mpp3, Serpinb6b and Pvrl3)." (PMID 38434966, 2024).
CCND2 also shares sentences with these, for which no sentence is quoted: multiple myeloma (13 papers); Hyperglycemia (5); gastric tumors (3); neuroblastoma (3); renal carcinoma (3); benign prostatic hyperplasia (2); cardiac disease (2); esophageal cancer (2); heart failure (2); Hyperinsulinemia (2); Hypertension (2); Macrocephaly (2); neuroectodermal tumor (2); non-Hodgkin lymphoma (2); pancreatic ductal adenocarcinoma (2); polymicrogyria (2); small cell lung carcinoma (2); testicular cancer (2); thyroid nodule (2); uterine corpus endometrial carcinoma (2); viral infection (2); acral melanoma (1); acute myocardial infarction (1); adenosarcoma (1); adult T-cell leukemia/lymphoma (1); asthma (1); Ataxia (1); bladder squamous cell carcinoma (1); bladder tumour (1); blood cancer (1).
A further 63 diseases each share a sentence with CCND2 in 1 paper.